AFP (alpha fetoprotein)
Diseases named in the same sentence as AFP in open-access papers (continued):
Sharing a sentence is not in itself a finding about the gene and the disease.
bone metastasis (11 papers, 2010 to 2024). Transfer of a neoplasm from its primary site to bones. "In summary, age, sex, marital status, T stage, N stage, surgery, chemotherapy, tumor size, AFP level, fibrosis score, bone metastasis, lung metastasis, and grade were independent prognostic factors for older patients with HCC." (PMID 37067674, 2024). "As can be seen, surgery and bone metastasis were the 2 most important factors affecting patient survival, followed by AFP level, chemotherapy, lung metastasis, tumor size, and radiotherapy." (PMID 39312373, 2024). "Six factors (bone metastasis, portal vein tumor thrombus, alpha-fetoprotein, radiation of tumor in liver, radiation dose and biologically effective dose) were considered potentially significant (P < 0.05)." (PMID 34395242, 2021). "Multivariate Cox regression analysis showed that sex, marital status, AJCC stage, tumor size, bone metastasis, lung metastasis, AFP level, surgery, radiotherapy, and chemotherapy were independent prognostic factors for CSS (P < .05), and they were used in the construction of the nomogram." (PMID 39312373, 2024). "The univariate and multivariate cox regression analysis successfully identified 13 independent prognostic factors including age, sex, marital status, T stage, N stage, surgery, chemotherapy, tumor size, AFP level, fibrosis score, bone metastasis, lung metastasis, and grade." (PMID 37067674, 2024). "The risk factors causing PM from HCC were age (P = 0.001), race (P < 0.001), primary tumor size (P < 0.001), T stage (P < 0.001), N stage (P < 0.001), alpha-fetoprotein (P < 0.001), bone metastasis (P < 0.001), brain metastasis (P < 0.001), and intrahepatic metastasis (P < 0.001)." (PMID 31440435, 2019). "Liver primary lesion surgery, orthopedic therapeutic surgery, number of bone metastasis, and AFP positive were further enrolled in the multivariate logistic analysis to correct for confounding factors (“Sites of bone metastasis” was excluded due to the collinearity with “Number of bone metastasis”)." (PMID 36386547, 2022). "In the present study, three patients had extrahepatic recurrence; one with bone metastasis showed elevated DCP, one with lymph node metastasis showed elevated AFP and AFP-L3, and one with lung metastasis tended toward elevated L3." (PMID 38137645, 2023). "The OTS group and the control group were compared in gender, age, pathological type, multiple bone metastases, sites of bone metastasis, pretreatment KPS score, α-fetoprotein (AFP), AFP-L3, and PIVKA." (PMID 36386547, 2022). "Stratified analyses show that predictive model based on bone metastasis, PVTT, AFP, and radiation dose was robust both for patients treated with SBRT or conventional fraction radiation." (PMID 34395242, 2021). "Four factors including bone metastasis (HR = 1.781, P = 0.026), PVTT (HR = 2.078, P = 0.015), AFP (HR = 2.098, P = 0.007) and radiation dose (HR = 0.535, P = 0.023) have significant potential to predict survival." (PMID 34395242, 2021). "These factors were bone metastasis, PVTT, AFP and radiation dose." (PMID 34395242, 2021). "In this study, 6 clinical characteristics were indicated to be associated with OS of patients according to univariable analysis, and 4 (bone metastasis, PVTT, AFP and radiation dose) of them were statistically significant in multivariable Cox regression analysis." (PMID 34395242, 2021). "On the other hand, serum AFP level never exceeded normal limit (< 20 ng/mL) in our patient since diagnosis of bone metastasis." (PMID 20500842, 2010).
ovarian germ cell tumor (11 papers, 2016 to 2025). A neoplasm that arises from the ovary and originates from germ cells. "Elevated preoperative levels of BHCG and AFP are nearly diagnostic of malignant ovarian germ cell tumors; however, these might be present in only 50% of cases." (PMID 27525145, 2016). "AFP is a valuable marker for ovarian germ cell tumors, and its levels play a significant role in both diagnosis and prognostic evaluation." (PMID 40430002, 2025). "Therefore, AFP is a crucial marker for the diagnosis and recurrence assessment of malignant ovarian germ cell tumors." (PMID 40430002, 2025). "Alpha fetoprotein (AFP) and beta HCG are used to detect the stages and treatment response of ovarian germ cell tumors." (PMID 36831617, 2023).
polio (11 papers, 2012 to 2024). "During this activity, population immunity for polio was assessed, and active case searches in community and health facilities for any missed AFP cases with an onset in last six months and the collection of stool samples from contacts were completed." (PMID 39066397, 2024). "It is important that Uganda’s achievements in polio surveillance be sustained since global efforts towards polio eradication identified AFP surveillance as an essential component of the eradication strategy." (PMID 30626358, 2019). "In view of this epidemic, Zambia responded with series of supplementary polio immunization activities (SIA) to protect the children against polio, and heightened AFP surveillance activities to promote early detection of possible silent circulation of polio virus transmission." (PMID 39078841, 2024). "Many adaptive strategies developed over the course of polio eradication had applicability across contexts, for example utilizing environmental surveillance in areas with poor AFP surveillance rates and creating temporary delivery outposts in hard-to-reach areas." (PMID 32787949, 2020). "Thus, 646 VDPV2 and 3256 Sabin 2 from AFP stools were destroyed in both Ibadan and Maiduguri polio laboratories." (PMID 30541484, 2018).
Telangiectasia (11 papers, 2013 to 2025). Telangiectasias refer to small dilated blood vessels located near the surface of the skin or mucous membranes, measuring between 0.5 and 1 millimeter in diameter. "Because of the IgG and IgA deficiency, cellular radiosensitivity, telangiectasia, and elevated AFP, we explored the possibility of an ATM-related dysfunction." (PMID 29255463, 2017). "Both patients presented with immunoglobulin deficiency, telangiectasia, cellular radiosensitivity, and increased alpha-fetoprotein (AFP) levels." (PMID 29255463, 2017). "Additional features of A-T that are not typically observed in CP include immunodeficiency, elevated alpha-fetoprotein (AFP), and telangiectasias." (PMID 41451872, 2025). "One study utilizing AFP for treatment of poikiloderma of Civatte observed a 65.0% improvement in erythema/telangiectasia and a 66.7% improvement in dyschromia with the average number of 1.4 treatments required for improvement." (PMID 25610668, 2014). "Clinicians may not be familiar with the wide range of clinical presentations of variant ataxia‐telangiectasia, where eye movements can be normal, conjunctival telangiectasia absent, neurological presentation mainly extrapyramidal, and AFP levels within normal range." (PMID 30549301, 2019).
anencephaly (10 papers, 2009 to 2025). A rare neural tube defect during pregnancy, resulting in the absence of a large portion of the brain and skull in the fetus. "Anencephaly is strongly associated with significantly elevated levels of alpha-fetoprotein in the mother’s blood, often exceeding normal levels by two and a half times." (PMID 39301375, 2024). "Perhaps the earliest example of prenatal screening is the use of a single second trimester maternal serum marker, α-fetoprotein (AFP), to identify pregnancies at high risk of anencephaly and spina bifida." (PMID 26237388, 2014). "In the 1870s, the increase in the alpha-fetoprotein (AFP) concentration in the maternal serum was first to be a indicator for anencephaly, and it is still widely used today." (PMID 38650623, 2024). "Anencephaly, for example, is characterized by an increase in alpha-fetoprotein and acetylcholinesterase levels in the maternal serum." (PMID 37686115, 2023). "If the AFP concentration in amniotic fluid is very high and the ultrasound examination does not reveal fetal anencephaly or other malformations, NPHS1 is a probable diagnosis." (PMID 17968594, 2009).
dysgerminoma (10 papers, 2007 to 2025). A malignant germ cell tumor characterized by the presence of a monotonous primitive germ cell population. "Specifically, all patients except those with dysgerminoma histology had an abnormal AFP." (PMID 40343905, 2025). "The AFP levels in patients with dysgerminomas were all normal." (PMID 38001671, 2023). "Among patients with elevated AFP levels, the median was highest in patients with YST (42,518 U/mL), followed by those with mixed GCT (14,761 U/mL), and dysgerminoma (1850 U/mL)." (PMID 37958463, 2023). "For Swyer syndrome with pure dysgerminomas, a screening is not useful because of the absence of known tumor markers such as AFP and beta-HCG." (PMID 38893276, 2024). "In general, dysgerminomas do not produce alpha fetoprotein, although borderline elevations (<16 ng/mL) are described in case series, but most often in the setting of mixed germ cell tumors that contain a yolk sac element." (PMID 33832117, 2021).
Encephalopathy (10 papers, 2015 to 2024). Encephalopathy is a term that means brain disease, damage, or malfunction. "Moreover, a decreased rate of encephalopathy, ascites, and serum AFP ≥ 400 ng/mL were observed in patients with low AGS (p = 0.023; p = 0.048; p = 0.011, respectively)." (PMID 36983238, 2023). "Cox proportional hazards regression model revealed that age, total bilirubin, ln (alpha‐fetoprotein [AFP]), encephalopathy (HE) score, sodium level, and international normalized ratio (INR) were independent risk factors of short‐term prognosis." (PMID 31769901, 2020).
gallbladder carcinoma (10 papers, 1993 to 2026). "Some scholars suggest that AFP-producing gallbladder carcinomas metastasize more frequently to the liver and have a poorer prognosis compared to those not producing AFP." (PMID 41357596, 2025). "As no additional metastases were detected, we diagnosed the patient with either AFP-producing gallbladder carcinoma (cT2aN0M0, cStage IIa, UICC 8th) or gallbladder metastasis from HCC." (PMID 36402065, 2022). "Essentially identical results were obtained for AFP from the patient with gallbladder carcinoma which metastasizes to the liver." (PMID 7679920, 1993). "Case 1 had only single ablation with US guidance using two laser fibers due to gallbladder carcinoma metastatic retroperitoneal lymphoma, and he had decrease in CEA and CA19-9 levels while AFP level was in normal." (PMID 27974691, 2017). "The normal tumor marker levels (AFP, CA19–9) were reassuring but not sufficient to rule out malignancy definitively, as they can be within normal limits in a subset of gallbladder cancers." (PMID 41466780, 2026).
intrauterine growth restriction (10 papers, 2018 to 2025). "The AFP level is also a commonly known predictor of pregnancy complications, e.g., preeclampsia, intrauterine growth restriction (IUGR), and placental abruption." (PMID 38379864, 2024). "Ratio of maternal serum alpha fetoprotein (AFP)/amniotic fluid AFP was suggested as a potential predictor for intrauterine growth restriction and preterm delivery in a small sample sized study." (PMID 30405914, 2018).
liver neoplasm (10 papers, 2012 to 2025). Tumors or cancers of the LIVER. "An elevated serum AFP with the finding of liver neoplasm can easily lead to a diagnosis of HCC in patients at risk." (PMID 35720017, 2022). "CT had high accuracy for diagnosing liver neoplasms in the under 2-year age population after AFP correlation." (PMID 38831055, 2024). "Liver tumors develop approximately 10 to 20 years after FP, frequently with a cirrhotic background and with elevated AFP." (PMID 38254797, 2024). "After a course of 9-month treatment, the PSC lesion shrank still, while HCC was evaluated as a progressive disease with an increase in the diameter of liver neoplasm, elevated alpha-fetoprotein, and enlarged abdominal lymph nodes." (PMID 35865468, 2022). "One of these markers is alpha-fetoprotein, a protein that is present in 60%–70% of patients with hepatocarcinoma, and represents the only clinical available marker of this liver neoplasm." (PMID 25558904, 2014). "At the second level of specificity we have tried to use liver tumour specific AFP promoter based fusion constructs." (PMID 25108398, 2014). "Alpha-fetoprotein (AFP) is still the main biomarker of liver neoplasm." (PMID 37434213, 2023). "Markers of liver tumours, such as Glypican-3, AFP and HepPar1, were present in HC-AFW1." (PMID 22666492, 2012). "Additionally, mild or moderately high AFP levels could be seen in the benign hepatic lesions, which may easily and wrongly suggest malignant liver tumors, so it is necessary to detect dynamic changes in AFP that is elevated." (PMID 29390333, 2017). "To date, no enrolled patient has demonstrated elevation in serum AFP level or developed liver neoplasms." (PMID 41193418, 2025). "Conventional B-mode US has been shown to be a rapid, non-invasive, cost-effective, and widely available tool for liver neoplasm screening, while B-mode US is less accurate and sensitive at differentiating HCC from benign FLLs without AFP measurement or alleviated AFP." (PMID 35720017, 2022).
thrombosis (10 papers, 2013 to 2025). "AFP levels were found to correlate significantly with size of lesion (r=0.1239, p=0.0411), presence of thrombosis (p<0.0001), and across BCLC stages (p<0.0001) and Okuda stages (p=0.03069)." (PMID 35226292, 2022). "The prognostic risk factors of HAS are related to infiltrating depth, portal vein thrombosis, vascular invasion, distant metastasis, pTNM stage, serum AFP levels, therapeutic regimen, and immunohistochemical staining." (PMID 33912455, 2021). "No vascular thrombosis was noted, and alpha-fetoprotein (AFP) was 2.89 ng/m." (PMID 40233638, 2025).
autoimmune hepatitis (9 papers, 2011 to 2025). Hepatitis caused by autoantibodies. "For example, it has reported that the elevation of AFP level can be caused by autoimmune hepatitis." (PMID 23763817, 2013). "An 18-year-old patient suffering from autoimmune hepatitis had markedly increased alpha-fetoprotein (aFP) levels (2,002 μg/L; normal <10 ug/L)." (PMID 21760772, 2011). "However, serum AFP has limited utility in HCC diagnosis as it can also increase in other non-HCC diseases, such as autoimmune hepatitis (AIH) and acute liver failure (ALF)." (PMID 37241155, 2023).
cervical carcinoma (9 papers, 2013 to 2025). A carcinoma arising from either the exocervical squamous epithelium or the endocervical glandular epithelium. "In cervical cancer patients, AFP was found to be negatively correlated with relative abundance of Rubrobacter sp. (P < 0.05), and CA199 was found to be positively correlated with relative abundance of Saccharomonospora sp. (P < 0.05)." (PMID 39101825, 2024). "In cervical cancer patients, AFP (correlation coefficient = −0.3714) were found to be negatively correlated (r = 0.4, 95% CI: 0.03 to 0.7) with relative abundance of Rubrobacter sp." (PMID 39101825, 2024). "Regarding cervical carcinomas, it should be noted that AFP-producing cervical carcinoma with fetal gut-like morphology has been reported." (PMID 34977100, 2021). "In addition, in cervical cancer patients, alpha-fetoprotein (AFP) (correlation coefficient = −0.3714) was negatively correlated (r = 0.4, 95% CI: 0.03 to 0.7) with Rubrobacter sp." (PMID 39101825, 2024). "Alpha-fetoprotein was frequently elevated in patients with ovarian germinoma, stromal tumors, and large-cell nonkeratinizing cervical cancer." (PMID 37594950, 2023).
Splenomegaly (9 papers, 2020 to 2024). Abnormal increased size of the spleen. "For OS, these included sex (p = 0.019), splenomegaly (p < 0.001), lymphocyte count (p = 0.014), aspartate transaminase (p = 0.038), albumin (p = 0.044), prothrombin time (p = 0.012), and alpha‐fetoprotein (AFP) (p = 0.015)." (PMID 35599583, 2022). "After adjusting splenomegaly, up-to-seven criteria, alpha fetoprotein and platelet count as confounders, VR remained as an independent factor for OS in patients received NA therapy undergoing TACE (HR, 0.772; 95% CI, 0.615-0.916), P=0.003)." (PMID 34745980, 2021). "Splenomegaly, up-to-seven criteria, alpha fetoprotein, total bilirubin, platelet count and sorafenib treatment after TACE were associated with OS in VR group." (PMID 34745980, 2021). "Reported clinical manifestations include: cholestasis (13/13, 100%), persistently elevated AFP (11/11, 100%), coagulopathy (11/11, 100%), hypoglycemia (9/13, 69%), splenomegaly (7/13, 54%), hyperammonemia (7/13, 54%), failure to thrive (8/13, 62%), and hepatomegaly (6/13, 46%)." (PMID 38641832, 2024). "Multivariate Cox regression analysis revealed that sex (p = 0.015), splenomegaly (p = 0.002), and AFP (p = 0.035) were risk factors associated with OS in patients with PLC treated with ICIs, and that sex (p = 0.023) and splenomegaly (p = 0.013) were risk factors associated with PFS." (PMID 35599583, 2022). "Among patients treated with ICIs with AFP levels ≥200 ng/ml, the OS of patients with splenomegaly was significantly lower than that of those without splenomegaly (p < 0.01)." (PMID 35599583, 2022). "Similarly, among patients with AFP levels ≥200 ng/ml, the PFS of patients with splenomegaly was significantly lower than that of those without splenomegaly (p = 0.04)." (PMID 35599583, 2022).
trisomy 21 (9 papers, 2012 to 2025). A chromosomal disorder consisting of the presence of an extra chromosome 21. "In the non-AMA group, the AUC was 0.784, 0.699 and 0.856 for maternal free β-hCG MoM, AFP MoM, and the risk value of Trisomy 21, respectively." (PMID 33317474, 2020). "Evaluation of the effect of IVF and ICSI on total hCG, free βhCG, AFP and uE3 as a marker for maternal serum screening for trisomy 21 in the 2nd trimester." (PMID 40567908, 2025). "The current screening for trisomy 21, 18 by applying markers such as maternal serum free human chorionic gonadotropin (free β-hCG) and alpha-fetoprotein (AFP) in second trimester has evolved into a routine obstetric examination." (PMID 35948592, 2022). "Traditionally, screening for trisomy 21 was based on maternal age and biochemical testing of second trimester (14–18 weeks) maternal serum AFP." (PMID 24156088, 2013). "Accordingly, we aim to unravel the physiology of these markers (PAPP-A, free hCGβ, hCG, AFP, uE3, inhA, and cell-free feto–placental DNA) and their regulation, focusing on the placenta and try to explain their abnormal variations in maternal serum in trisomy 21-affected pregnancies." (PMID 37108840, 2023). "However, it is still controversial whether an increased maternal serum AFP level is a reliable indicator of trisomy 21 in early pregnancy." (PMID 34750768, 2022). "For trisomy 21, the results revealed that the substitution of AFP-L2 for AFP improved the IDI and NRI by 9.56% and 26.50%, respectively, that AFP-L3 substitution for AFP augmented the IDI and NRI by 12.34% and 26.70%, respectively." (PMID 35948592, 2022). "This study aimed to compare the level of βhCG and free AFP of the mother in the middle trimester of ART pregnancies and Non-ART pregnancies in trisomy 21 screening (second round)." (PMID 40567908, 2025).
esophageal squamous cell carcinoma (8 papers, 2017 to 2022). Esophageal squamous cell carcinoma (ESCC) is a type of esophageal carcinoma (EC) that can affect any part of the esophagus, but is usually located in the upper or middle third. "Currently, with respect to HCC, a number of TAAs have been identified: α-fetoprotein (AFP), New York esophageal squamous cell carcinoma-1 (NY-ESO-1), melanoma antigen gene (MAGE) family, glypican-3 (GPC3), and so on." (PMID 30116759, 2018). "Indeed, cellular response has been detected against alpha-fetoprotein (AFP), glypican-3 (GPC-3), melanoma-associated genes (MAGE)-1, 3, and 10, synovial sarcoma X (SSX)-2, and New York-esophageal squamous cell carcinoma-1 (NY-ESO-1) in blood, as well as in the tumors of HCC patients." (PMID 35216137, 2022).